PRNP (prion protein (Kanno blood group))
Diseases named in the same sentence as PRNP in open-access papers (continued):
Sharing a sentence is not in itself a finding about the gene and the disease.
depression (6 papers, 2016 to 2024). "The PRNP gene is also thought to have a role in Huntington-disease-like neurodegenerative disorder in humans, which is characterized by behavioral and psychiatric symptoms, including anxiety, depression, aggression, and irritability." (PMID 39766878, 2024).
diabetes mellitus (6 papers, 2009 to 2024). A metabolic disorder characterized by abnormally high blood sugar levels due to diminished production of insulin or insulin resistance/desensitization. "Specifically, five genes—ATF4, ATP1A1, B2M, CYBA, and PRNP—emerged with the highest inference scores in the context of T2D and Diabetes Mellitus, suggesting that these genes play critical roles in the molecular mechanisms underlying these conditions." (PMID 39926598, 2024).
viral infection (6 papers, 2010 to 2024). "PRNP and PrP are upregulated during virus infection by HIV-1, VSV, MLV, HCV, adenovirus 5, and Epstein–Barr virus, and in brains of HIV-1- and SIV-infected patients and macaques." (PMID 33081049, 2020).
cerebral amyloid angiopathy (5 papers, 2013 to 2022). "Genetic prion diseases, including familial CJD, GSS, FFI, and PrP-cerebral amyloid angiopathy (PrP-CAA) are linked to point mutations or insertions in the PRNP gene encoding PrPC." (PMID 24369467, 2013). "In Prion-Protein Cerebral Amyloid Angiopathies (PrP-CAA), which are associated with nonsense mutations in the PRNP gene, the main histologic feature is the co-existence of numerous intraneuronal Tau aggregates with APrP in the vascular compartment." (PMID 34128081, 2021).
variant Creutzfeldt-Jakob disease (5 papers, 2008 to 2022). A form of Creutzfeldt-Jakob disease that is most commonly contracted after consuming meat from an animal suffering from bovine spongiform encephalopathy. "So far, all clinical cases of new variant Creutzfeldt-Jakob disease (vCJD), thought to result from the Bovine Spongiform Encephalopathy (BSE) prion agent, have shown Methionine–Methionine (M/M) homozygosity at the M129V polymorphism of the PRNP gene." (PMID 19495414, 2009).
amyotrophic lateral sclerosis (4 papers, 2013 to 2025). Amyotrophic lateral sclerosis (ALS) is a neurodegenerative disease characterized by progressive muscular paralysis reflecting degeneration of motor neurons in the primary motor cortex, corticospinal tracts, brainstem and spinal cord. "It is also found that PRNP 129 polymorphism is related with AD in a polish study, but not related with AD and amyotrophic lateral sclerosis (ALS) in other study." (PMID 23671608, 2013).
systemic amyloidosis (4 papers, 2015 to 2025). "PrP systemic amyloidosis is increasingly recognized as a novel inherited prion disease (IPD) syndrome caused by PRNP C-terminal truncating mutations." (PMID 40611688, 2025). "This mutation strengthens the evidence for an association between C-terminal truncation mutations of PRNP and the PrP systemic amyloidosis phenotype and we provide results of plasma biomarkers." (PMID 40611688, 2025). "The prion protein can form amyloid deposits outside of the CNS in the presence of selected mutations of the PRNP gene, leading to PrP systemic amyloidosis, or in the context of variant Creutzfeldt-Jakob disease." (PMID 32754033, 2020). "Different PRNP mutations are associated with distinct clinical and neuropathological phenotypes: CJD, FFI, GSS, PrP-cerebral amyloid angiopathy and a recently described PrP systemic amyloidosis." (PMID 25880443, 2015).
colon adenocarcinoma (3 papers, 2017 to 2024). "Surprisingly, both targets of miR-148a allowed us to predict the overall survival in colon adenocarcinoma patients with a statistical significance: logrank test p was equal to 0.0133 and 0.0119 for ITGA5 and PRNP, respectively." (PMID 34135940, 2021).
lung adenocarcinoma (3 papers, 2019 to 2025). A carcinoma that arises from the lung and is characterized by the presence of malignant glandular epithelial cells. "CL1-1 and CL1-5, lung adenocarcinoma cell lines with varying metastatic and invasive capabilities, have shown distinct levels of PRNP expression, with higher expression in the highly invasive CL1-5 cells." (PMID 39972491, 2025).
adenoma (2 papers, 2021 to 2024). A neoplasm arising from the epithelium. "Turning to CRC patients, we analyzed the expression profile of PRNP along disease progression from normal to adenoma to carcinoma." (PMID 38589873, 2024). "As observed with NR3C1, TSC22D3 transcripts are reduced in adenoma versus normal tissue but further induced at the adenoma-to-carcinoma progression; they strongly correlate with PRNP levels, including in the large GSE39582 dataset and are enriched in CMS4 CRC." (PMID 38589873, 2024). "In three distinct datasets GSE8671, GSE20916 and GSE4183, we recurrently found decreased expression of PRNP transcripts in adenoma versus normal tissue, contrasting with the increase in the expression of several Wnt target genes including AXIN2." (PMID 38589873, 2024).
Autoimmunity (2 papers, 2012 to 2025). The occurrence of an immune reaction against the organism's own cells or tissues. "Though the correlation of PRNP with RA manifestation has been explored the least, basophil enrichment raises possibilities about its function in allergic inflammation and autoimmunity." (PMID 41021591, 2025).
colitis (2 papers, 2013 to 2015). Inflammation of the colon. "PRNP expression was increased both in submucosal inflammatory cells and to some degree also in epithelial cells, while a substantial down-regulation of PPARγ was evident in the epithelium after induction of colitis." (PMID 23382912, 2013). "PRNP (PrPc) mRNA was significantly up-regulated in TNBS-colitis." (PMID 23382912, 2013).
cortical blindness (2 papers, 2011 to 2023). "Therefore, HvCJD patients, especially those with PRNP mutations, should be informed of the possibility of cortical blindness and its impact on their quality of life and family, and any changes in their vision should be investigated promptly." (PMID 37243178, 2023).
demyelinating polyneuropathy (2 papers, 2017 to 2020). Polyneuropathy that is characterized by demyelination of axons. "Moreover, a patient with two pathogenic PRNP mutations was reported to develop an early onset peripheral demyelinating neuropathy." (PMID 33180885, 2020).
encephalopathies (2 papers, 2020 to 2023). "Genetic human prion diseases are a group of inherited encephalopathies directly associated with different mutations in PrP-encoding gene PRNP, including more than 50 different mutations worldwide." (PMID 32998248, 2020).
Hypoglycemia (2 papers, 2013 to 2024). A decreased concentration of glucose in the blood. "Recent studies have proven that oxidative stress mimicked by Cu2+, hyperbaric oxygen, or hypoglycemia enhances PRNP expression and that the lack of PrPC increases the level of intracellular oxidative stress." (PMID 23967259, 2013).
liver cancer (2 papers, 2024). An epithelial or non-epithelial malignant neoplasm that arises from the liver. "Later, the Venn diagram revealed that SCIN could play a role in liver cancer through ABCC 1, CAPG and PRNP, and the relationship between the three genes and SCIN in liver cancer was verified in GSCA database." (PMID 39108273, 2024).
mastitis (2 papers, 2015 to 2024). Inflammation of breast tissue during lactation or postpartum due to an obstructed duct or infection. "For example, GM chickens expressing a short-hairpin RNA suppressed avian influenza transmission, PrPC-deficient (PRNP−/−) cattle were resistant to prions (BSE, bovine spongiform encephalopathy), and GM cows that secreted lysostaphin resisted S. aureus-induced mastitis." (PMID 25874566, 2015).
meningioma (2 papers, 2019 to 2025). A generally slow growing tumor attached to the dura mater. "Thirdly, the biological roles and specific mechanisms underlying FOXM1 and PRNP in meningiomas warrant in-depth exploration." (PMID 41050085, 2025). "Altogether, among the key oxidative stress-related genes, FOXM1 and PRNP were experimentally evidenced to be up-regulated in meningiomas." (PMID 41050085, 2025). "FOXM1 and PRNP were experimentally evidenced to be highly expressed in meningioma cells, and their knockdown hindered cell growth and migration and triggered ROS accumulation." (PMID 41050085, 2025). "Further western blot proved the higher expression of FOXM1 and PRNP in two meningioma cells vs. HMC cells, without significant difference in SEPP1 expression." (PMID 41050085, 2025). "Silence of FOXM1 or PRNP effectively attenuated the growth and migration of meningioma cells as well as accelerated intracellular ROS accumulation." (PMID 41050085, 2025). "Among the key oxidative stress-related genes, FOXM1 and PRNP were experimentally proven to be up-regulated in two human meningioma cells (CH-157MN and IOMM-Lee) vs. one human meningeal cell (HMC)." (PMID 41050085, 2025). "Silence of FOXM1 and PRNP was thus evidenced to induce the excessive accumulation of ROS in meningioma cells." (PMID 41050085, 2025). "In our future studies, we will further validate the clinical value of the novel oxidative stress-based classification and the two oxidative stress-related genes (FOXM1 and PRNP) in meningiomas." (PMID 41050085, 2025). "Moreover, FOXM1 and PRNP were experimentally evidenced as promising treatment vulnerabilities against meningiomas." (PMID 41050085, 2025). "This study, for the first time, reported the biological implication of PRNP in meningiomas." (PMID 41050085, 2025). "Hence, the silence of FOXM1 and PRNP lowered the proliferation and migration of meningioma cells." (PMID 41050085, 2025). "It was noted that most of the oxidative stress-related genes presented differential expression between high-grade and low-grade meningiomas, especially AOX1, FOXM1, GPX3, PRNP, and SEPP1." (PMID 41050085, 2025). "This study further experimentally validated the key oxidative stress-related genes: AOX1, FOXM1, GPX3, PRNP, and SEPP1 in human meningeal cells (HMC) and two meningioma cells (CH-157MN and IOMM-Lee)." (PMID 41050085, 2025). "Oxidative stress-related genes such as AOX1, FOXM1, GPX3, PRNP, and SEPP1 were differentially expressed between high- and low-grade meningiomas." (PMID 41050085, 2025).
Myoclonus (2 papers, 2022). Very brief, involuntary random muscular contractions occurring at rest, in response to sensory stimuli, or accompanying voluntary movements. "In the sCJD subgroup alone, we found evidence (P < 0.001) that myoclonus (more prevalent in MM and VV genotypes), tremor (MV and VV genotypes), supranuclear ophthalmoparesis (MV genotype), and alien limb phenomenon (MM genotype) were modified by PRNP codon 129 genotype." (PMID 35841311, 2022).
ovarian carcinoma (2 papers, 2022 to 2023). A malignant neoplasm originating from the surface ovarian epithelium. "Overexpression of ferroptosis-related gene prion protein (PRNP) inhibits ovarian cancer proliferation and invasion." (PMID 37842240, 2023). "Next, we further explore the role of PRNP in proliferation, migration, and invasion ability of ovarian cancer cells." (PMID 36213323, 2022). "First, we overexpressed the expression of PRNP in two ovarian cancer cell lines SKOV3 and HO8910." (PMID 36213323, 2022). "To further validate the expression level of PRNP in ovarian cancer, we explored the transcriptional level of PRNP in two independent public ovarian cancer GEO datasets and found that compared to the normal ovarian tissues, the mRNA levels of PRNP were obviously decreased in ovarian cancer tissues." (PMID 36213323, 2022). "In addition, we found that the protein expression level of PRNP was significantly downregulated in ovarian cancer tissues based on UALCAN database." (PMID 36213323, 2022). "Furthermore, we explored the correlation between the PRNP expression and clinicopathological factors of ovarian cancer patients." (PMID 36213323, 2022). "Moreover, through in vitro experiments, we further validated that the transcriptional and protein expression levels of PRNP were significantly decreased in ovarian cancer cells SKOV3 and HO8910 compared with the normal ovarian cells IOSE." (PMID 36213323, 2022). "We further analyzed the biological function and pathways of PRNP in ovarian cancer." (PMID 36213323, 2022). "In this study, three ferroptosis-related genes PRNP, ACSL1, and CP were picked out as the co-DEGs among different ovarian cancer datasets, with significantly decreased expression of PRNP and ACSL1 and increased expression of CP in ovarian cancer tissues when compared with normal ovarian tissues." (PMID 36213323, 2022).
Wilson disease (2 papers, 2014 to 2025). A very rare inherited multisystemic disease presenting non-specific neurological, hepatic, psychiatric or osseo-muscular manifestations due to excessive copper deposition in the body. "Other reports have linked variation in the progress of Wilson’s disease with the common p.Met129Val polymorphism in PRNP." (PMID 24555712, 2014).
amyloid cardiomyopathy (1 paper, 2013). "All macaques are homozygous for methionine on PRNP codon 129; thus, prion-amyloid cardiomyopathy cannot be related to polymorphic codon 129 in our study." (PMID 23735198, 2013).
Atrophy (1 paper, 2023). Any weakening or degeneration, especially through lack of use. "Regional patterns of PRNP expression in the healthy brain correlated with regional patterns of diffusion signal abnormalities and atrophy in sCJD." (PMID 36744645, 2023).
Chorea (1 paper, 2022). Chorea (Greek for 'dance') refers to widespread arrhythmic involuntary movements of a forcible, jerky and restless fashion. "Further genetic investigation, including SETX and other chorea-related genes (i.e., ADCY5, PRNP, and VPS13A) are needed, but are lacking due to limitations of laboratory conditions." (PMID 36596053, 2022).
ciliopathy (1 paper, 2022). A genetic disorder of the cellular cilia or the cilia anchoring structures, the basal bodies, or of ciliary function. "The targets of CREBP1 found from among the genes shared between the HLHS and ciliopathy interactomes were EP300, PRNP, SMAD3, SUMO1 and TBX6, while the targets of ALX4 were JUN and TCF7L2." (PMID 35456433, 2022).
E. coli infection (1 paper, 2014). "E. coli infection induced an increase in the PRNP mRNA level." (PMID 25058617, 2014). "In this study, we examined the effect of E. coli infection on the expression of the pro-inflammatory cytokines IL-1β, IL-6, and TNF-α in PRNP-knockout macrophages." (PMID 25058617, 2014).
Ecchymosis (1 paper, 2017). A purpuric lesion that is larger than 1 cm in diameter. "Multifocal ecchymosis and petechial hemorrhages were observed in four of eight PRNP+/+ goats and five of eight PRNPTer/Ter goats receiving LPS." (PMID 29270176, 2017).
Familial advanced sleep-phase syndrome (1 paper, 2018). "Serine to glycine mutation in PER2 and mutation in casein kinase Iδ gene (CSNK1D) develop familial advanced sleep phase syndrome (FASPS) whereas point mutation in PRNP causes fatal familial insomnia (FFI)." (PMID 29607311, 2018).
Hunter’s syndrome (1 paper, 2025). "The PRNP locus on chromosome 20 encodes the prion protein implicated in multiple neurodegenerative diseases, and IDS gene on chromosome X is associated with Hunter’s syndrome, a lysosomal storage disease." (PMID 39789389, 2025).
intestinal tumors (1 paper, 2024). "We first found that PRNP mRNA levels were elevated in intestinal tumors versus normal tissue, whatever the genetic status (hetero- or homozygous) of the mice." (PMID 38589873, 2024).
myotonic dystrophy (1 paper, 2025). An inherited progressive disorder affecting the muscles. "Unlike disorders with repeated expansions (e.g., myotonic dystrophy), FFI results from a point mutation (D178N in the PRNP gene), and lacks the known molecular mechanism of anticipation." (PMID 41107634, 2025).
Nasu-Hakola disease (1 paper, 2020). "In patients diagnosed with AD we found three C9orf72 expansions, nine DVs in MAPT, five in CSF1R, two in GRN, three in PRNP and one each in SQSTM1, TARDBP and VCP, as well as a homozygous TREM2 DV normally associated with Nasu-Hakola disease." (PMID 30279455, 2020).
parkinsonian disorder (1 paper, 2025). A group of disorders which feature impaired motor control characterized by bradykinesia, MUSCLE RIGIDITY; TREMOR; and postural instability. "Other repeat expansion genes, including ATXN3, CACNA1A, and PRNP, typically associated with parkinsonian disorders, do not exhibit an association with PD in our cohort." (PMID 41009775, 2025).
prostate tumor (1 paper, 2022). "In vitro tests on prostate tumor spheroids revealed a relationship between ROS levels and elevated PRNP expression." (PMID 36432484, 2022).